TWIST1 (twist family bHLH transcription factor 1)
Diseases named in the same sentence as TWIST1 in open-access papers (continued):
Sharing a sentence is not in itself a finding about the gene and the disease.
tumor (continued). "Twist1, a transcription factor that drives metastasis, was identified and characterized as a targetable “self” tumor-associated antigen in 4T1 tumor cells." (PMID 33669155, 2021). "Twist1 overexpression is linked to tumor malignancy early in oncogenesis and has been shown to stimulate tumor progression." (PMID 34577566, 2021). "Twist1 upregulation was also associated with a larger tumor size and higher TNM stage and with lymph node metastases." (PMID 34575184, 2021). "Induction of MYC and Twist1 expression is associated with tumor initiation and rapid onset of macrophage infiltration in early tumors which increases during tumor progression." (PMID 31933479, 2020). "Twist1 has been shown to be an important gene product that can enable mouse and human tumor cell lines to acquire the ability to metastasize associated with EMT." (PMID 31933479, 2020). "We also examined if a correlation exists between Twist1 expression and CIN for which we compared Twist1 expression with tumor mutation burden and copy number alterations (CNAs)." (PMID 32337580, 2020). "TWIST1 had a stronger association with tumor stage, as it had relatively smaller p-values than ADAM22 in both cohorts." (PMID 32629858, 2020). "Various epithelial and mesenchymal markers such as VI, N-cad and E-cad, Slug, Snail and Twist1 are associated with tumor progression." (PMID 31969493, 2020). "TWIST1 has been shown to be associated with tumor recurrence, metastasis and poor prognosis in different types of human cancers." (PMID 31645542, 2019). "Further, RUNX1, ZEB1 or TWIST1 expression didn’t show association with clinicopathological features in any of the analyzed tumor types." (PMID 31655611, 2019). "High Src-1 expression and high Twist1 expression were both associated with advanced tumor stage, distant metastasis and unfavorable prognosis." (PMID 30973923, 2019). "It was observed that expression of Twist1 is associated with the acquisition of stemness properties by tumor cells and increased metastasis." (PMID 31569731, 2019). "TWIST1 encodes a basic helix-loop-helix transcription factor, which promotes tumour cell invasion and metastasis in multiple human cancers." (PMID 30944663, 2019). "In the present study, we have found that Src-1 and Twist1 were aberrantly upregulated in human NPC tissues, and upregulation of Src-1 or Twist1 was associated with advanced tumor stage, distant metastasis and unfavorable prognosis." (PMID 30973923, 2019). "The results also showed that Twist1 expression in CAC was significantly closely associated with tumor differentiation, gross type, invasion, LNM stages, and TNM stages." (PMID 30021598, 2018). "The positive association between lncATB and Twist1 was further confirmed in resected tissues from tumour xenografts." (PMID 30518916, 2018). "The results of this study showed the expression of Twist1 in CAC to be positively associated with tumor differentiation, gross type, invasion, and LNM stages and TNM stages." (PMID 30021598, 2018). "Many of the EMT inducing transcription factors such as Snail1, Snail2/slug, ZEB1, ZEB2, FOXC2 and TWIST1 have been associated with tumor invasion and metastasis." (PMID 29202800, 2017). "In agreement with its role in embryonic cell migration, Twist1 overexpression is associated with the increase in tumor cell migration, invasion, and metastasis." (PMID 28774312, 2017). "Bcl-2 and Twist1 overexpression was associated with a poor pathological grade and tumor prognosis, and the two factors functions as a complex." (PMID 28032603, 2017). "Our networks showed a group of conserved associations between the miR-200 networks inferred from tumour and control data, this association core is conformed by miR-200 miRs and known transcription factors such as: TWIST-1, TWIST-2, ZEB-1 and ZEB-2." (PMID 29051564, 2017).
tumor (continued). "Tumor-derived cells elicited an epithelial-mesenchymal transition associated with upregulation of Zeb1 and Twist1/2 and enhanced tumor initiating and invasive capacities." (PMID 28740236, 2017). "EMT-associated genes promote cancer cell plasticity and tumor metastatic spread, and the process can be induced by some factors, such as TWIST1 and SNAIL." (PMID 27724883, 2016). "The ability of triterpenes is evidence to inhibit the inflammation in the tumor micron-environment associated with greater reduction of Cox-2 and Twist1 proteins more inhibition of activation of IGF-1R, Stat3, and Src." (PMID 27378920, 2016). "By the contrary, ectopic expression of Twist1 results in loss of E-cadherin-mediated cell-cell adhesion and activation of mesenchymal markers, both events contributing to tumor metastasis." (PMID 26985909, 2016). "Since TGFβ acts as a tumor suppressor by inhibiting cell proliferation, tumors overexpressing Twist1 and harboring inactivating mutations of TGFβ-pathway-members are highly likely to overcome growth inhibition, while being able to collectively invade." (PMID 27105506, 2016). "Among the transcripts in the DTC signature, only TWIST1 expression was significantly associated with early tumor relapse." (PMID 26378808, 2015). "Twist1 overexpression was frequently found in tumor tissues from NSCLC patients and associated with a significantly lower survival rate." (PMID 26360779, 2015). "We observed higher SLUG expression in clinically less aggressive tumors (lower grade, lower proliferation) and higher TWIST1 expression was associated with higher tumor stage." (PMID 26194471, 2015). "Here, we have shown that in the setting of TWIST1 and N-cadherin deficiency, metformin-mediated anti-tumor activity is AMPK dependent in different cancer tissues." (PMID 26359363, 2015). "Mediated by the ability of MMSET-mediated activation of TWIST1, a gene implicated in tumor-associated EMT and invasion, these data suggest that deregulated MMSET results in aberrant epigenetic gene regulation, leading to tumor progression and metastasis." (PMID 25566498, 2014). "The co-expression analysis suggested an association between stromal content of the tumor tissue and TWIST1 mRNA expression levels." (PMID 22967435, 2012). "More importantly, they found that, although rare in their hands, nuclear expression of TWIST1 protein in the epithelial tumor cell compartment to be associated with poor prognosis (OS)." (PMID 22967435, 2012). "We observed that EGF induced nuclear localization of the MUC1 cytoplasmic domain leading to expression of genes linked to tumor cell invasion and metastasis including TWIST1, SNAI1 and SNAI2." (PMID 22586492, 2012). "Several studies suggest that the TWIST1 gene is a novel oncogene that is associated with tumor formation and/or metastatic spread." (PMID 21037858, 2010). "Twist1 deficiency in ECs substantially improved the survival of tumor-bearing mice; more than half of Twist1 knockout mice were alive at days 28 and 23 post-tumor induction in GL261 and RCAS models, respectively, compared to the control group, where all the mice died." (PMID 38416830, 2024). "Moreover, there seems to be an association between Twist1 expression levels and tumor stage while Twist1 expression appears to be negatively correlated with MT1 expression." (PMID 38473317, 2024). "Interestingly, Twist1 is also implicated in vascularization both during development and in tumor models." (PMID 37208442, 2023). "In the present study, we confirmed the positive association of overexpressed TYMS with upregulated TWIST1 and N-cadherin mesenchymal markers, whose expressions demonstrate a predisposition toward extracellular matrix degradation and further tumor invasion and metastasis." (PMID 37894370, 2023). "Additionally, high Twist1 protein expression was associated with several genes and pathways known to have roles in aggressive tumor biology." (PMID 36900319, 2023).
tumor (continued). "In the same way, increased cell motility and EMT are linked to TWIST1 expression in tumor cells, which suggests that TWIST1 may play a part in metastasis." (PMID 38139368, 2023). "Twist1, as a member of the basic helix–loop–helix family of transcription factors, has multiple functions that are associated with the pathogenesis of fibrotic diseases and tumor progression." (PMID 35182235, 2022). "Such ECM modifications associated with TWIST1 expression could be responsible for a “pro-neoplastic” stromal phenotype, offering less resistance for the invasive cells to escape the primary tumor site and form metastasis." (PMID 35022561, 2022). "High Twist1 expression in cancers has been linked to metastasis and tumor cell invasion." (PMID 34577566, 2021). "In addition, we found that the expression of Twist1, a tumor metastasis-associated transcription factor, was upregulated in P.g-LPS-treated CAL27 and SCC15 cells." (PMID 33542221, 2021). "Additionally, overexpression of the twist-related protein 1 (Twist1) and GLUT1 genes are associated with many tumors, and Twist1 is a crucial factor for tumor metastasis." (PMID 33920726, 2021). "These in vivo observations suggest that Twist1 could be a therapeutic target to reduce muscle mass loss in tumor and other chronic debilitating diseases, not only to improve quality of life, but also to increase disease-free survival." (PMID 32655411, 2020). "Tumor associated macrophages are required for Twist1 to induce metastasis of MYC-HCC." (PMID 31933479, 2020). "Expression of Twist1 and Twist2 in human solid tumors has been associated with tumor progression." (PMID 31921617, 2019). "Overall, these results demonstrated that aberrantly upregulated Twist1 expression was associated with poor prognosis, tumor migration and invasion, thus Twist1 could be prognostic biomarkers and potential therapy targets for NPC patients." (PMID 30973923, 2019). "In experimental models, MARCKS overexpression was shown to suppress cellular senescence and boost the activation of AKT/TWIST1 (Protein kinase B/Twist-related protein 1) signaling to sustain the cancer-associated fibroblasts features, thus supporting tumor cells growth and invasion." (PMID 29295532, 2017). "Furthermore, MTDH is associated with the suppression of Twist1 expression, supporting the switch of tumor phenotype from mesenchymal to epithelial cells to accelerate metastatic colonization with epithelial plasticity." (PMID 29029495, 2017). "Accumulating evidence has shown that Twist1 is positively associated with tumor angiogenesis." (PMID 28099910, 2017). "Moreover, miR-186 and Twist1 were associated with larger tumor size and advanced clinical stage of GC." (PMID 27835599, 2016). "In addition to FN1 and SPARC, other well-established EMT-associated genes are also upregulated in these tumor samples following letrozole treatment including TWIST1, SNAI2, ZEB1, and ZEB2." (PMID 24944582, 2014). "Therefore, we studied the association of TWIST1 mRNA expression with tumor stromal content in more detail." (PMID 22967435, 2012). "The EGFR mutated SNAI1 reactivated tumor express TWIST1, VIM and CDH2 (sample 288) suggesting that TWIST1 and SNAI1 might interact to drive full mesenchymal phenotype." (PMID 22272264, 2012). "Using linear regression we found four DNA methylation markers, MT2, SFRP2, TFAP2A, and TWIST1, that showed individual association with tumor subtype at p<0.05 significance level, however, after adjusting for multiple comparisons, none of these associations remained statistically significant." (PMID 22028801, 2011). "Similarly, average tumor sizes in control mice were two- to fourfold higher than that in Twist1-deficient mice at days 22 to 25 in the GL261 model and at days 17, 19, and 21 in the RCAS model, collectively suggesting an important role of endothelial Twist1 in GBM growth." (PMID 38416830, 2024).
tumor (continued). "However, more experimental evidence is needed to determine whether the tumor cell proliferation could be regulated by the gain/loss of function of Twist1." (PMID 37784111, 2023). "Moreover, based on the expression of EMT hallmark genes including SNAI2, N-cadherin, Vimentin, ZEB1, ZEB2, SNAI1, Fibronectin, TWIST1 and E-cadherin, we found that patients with high risk score distinctly exhibited a mesenchymal phenotype, suggesting a higher tumor malignancy." (PMID 36505846, 2022). "Also some novel biomarkers were investigated to predict the survival outcome of PSC, such as CD8+ tumor-infiltrating lymphocytes, the epithelial−mesenchymal transition transcription factors (Twist1), the change of neutrophil-to-lymphocyte ratio, KRAS mutations and c-MET overexpression." (PMID 34136380, 2021). "MYC and Twist1 cooperate and their sustained expression is required to elicit a transcriptional program associated with the activation of innate immunity, through secretion of a cytokinome that elicits recruitment and polarization of tumor associated macrophages (TAMs)." (PMID 31933479, 2020). "Similarly, module 6 contains EMT inducer TWIST1, many extracellular matrix genes, as well as genes associated with senescence and autophagy, collagen genes, and the well validated predictor of tumor resectability, POSTN." (PMID 27287041, 2016). "This way, Twist1 helps tumor cells break through basement membranes and move into the stroma around them." (PMID 41596524, 2026). "In contrast, the expression levels of STAT3 downstream target genes—such as VEGFA, IL-6, MMP13, Bcl2, and Twist1—remained comparable across all experimental groups, likely due to tumor excision occurring at a stage when metastasis was already underway." (PMID 40806360, 2025). "These BCSCs show enhanced self-renewal and tumor initiation abilities and express markers like TWIST1 and FOXF2." (PMID 39858015, 2025). "This study systematically reviews the molecular mechanisms by which NPs and TCM formulations inhibit VM formation across various tumor types, and summarizes multiple core intervention targets, including VE-cadherin, EphA2, MMPs, Twist1, HIF-1α, and PI3K/Akt." (PMID 41019994, 2025). "Intravenous or intranasal administration of tumor or serum-derived EVs were used to investigate the role of EVs-packaged Twist1 in depressive-like behaviors in mice." (PMID 40963917, 2025). "Genetic knockdown of Twist1 in tumor cells or pharmacological inhibition of EVs secretion (GW4869) reverses these effects." (PMID 40963917, 2025). "The protein stability of Twist1 is dynamically regulated by E3s and DUBs, which promote EMT and tumor metastasis by stabilizing Twist1." (PMID 41208892, 2025). "We demonstrated that EVs-packaged Twist1 derived from tumor cells induced dendritic atrophy and elicited depressive-like behaviors." (PMID 40963917, 2025). "(E) Representative IHC images showing the levels of ECHS1, GCDH, YEATS2, H3K27cr, and Twist1 in HNC normal vs. tumor tissue samples (n=8) (Scale bar, 100 μm)." (PMID 40810390, 2025). "For example, the group of 1055 genes possessing 361 members of the “biological regulation” item includes the TWIST1 gene that promotes tumor cell invasion and metastasis." (PMID 40869408, 2025). "At the cellular level, butein triggers miR-186-5p-induced modulation of TWIST1 expression, thereby inhibiting the growth of tumor spheroids, cell invasion, bioenergetics, and cisplatin resistance in the three PM cell lines." (PMID 40149313, 2025). "Mechanistically, tumor-derived EVs-packaged Twist1 induced defective morphogenesis of dendrites of pyramidal neurons in the mPFC by inhibiting peroxisome proliferator-activated receptor δ (PPAR-δ)." (PMID 40963917, 2025). "Overall, our findings support the association of tumor cells-derived Twist1 with elevated Twist1 in the mPFC of tumor-bearing mice, suggesting the pro-depressant effects of tumor cells-derived Twist1." (PMID 40963917, 2025).
tumor (continued). "Twist1 represses E-cadherin transcription, promoting tumor cell migration, invasion, and metastasis." (PMID 41208892, 2025). "This modulation of TWIST-1 reduced tumor sphere growth, cisplatin resistance, invasion and bioenergetics in the tested PM cells." (PMID 40149313, 2025). "Collectively, these findings confirm that tumor cell-derived EVs-packaged Twist1 promotes neuronal dendritic atrophy phenotype." (PMID 40963917, 2025). "Mechanistically, studies have revealed a spatially restricted Twist1/SATB1-mediated sequential transcriptional activation mechanism through which tumor ECs produce osteoblasts and promote an immunosuppressive macrophage (Mφ) phenotype." (PMID 40565303, 2025). "More importantly, we identified the key role of tumor cell-derived EVs-packaged Twist1 in neuronal morphogenesis regulation." (PMID 40963917, 2025). "Downregulation of FAM64A inhibited tumor growth and lung metastasis in mice, possibly by suppressing TWIST1 ubiquitination and degradation via the E3 ubiquitin ligase STUB1 and activating the Wnt/β-catenin signaling pathway." (PMID 40424038, 2025). "The EMT is considered a cellular process to induce cell stemness, which causes tumor metastasis and treatment resistance, for instance, ZEB1, SNAI1, and TWIST1." (PMID 39827156, 2025). "Meanwhile, it was found that Twist1 mRNA levels in tumor-derived EVs were reduced in Twist1 shRNA-expressing 4T1 cells compared to control shRNA-expressing cells." (PMID 40963917, 2025). "In our model, knockdown of Twist1 by intra-mPFC injection of lentivirus prevents depressive-like behavior in tumor-bearing mice, suggesting that tumor-derived EVs are more likely to carry Twist1 mRNA." (PMID 40963917, 2025). "Conversely, knockdown of Twist1 in tumor cells blocked SDEVs-elicited aberrant dendritic structures." (PMID 40963917, 2025). "Among these regions, Twist1 mRNA levels were upregulated in the mPFC and hippocampus of tumor-bearing mice." (PMID 40963917, 2025). "Clinically, elevated Twist1 correlates with increased lymph node metastasis, distant metastasis, and advanced tumor stage across multiple cancers." (PMID 41208892, 2025). "Quantitative polymerase chain reaction and western blot were used to detect the levels of Twist1 mRNA and protein from tumor-derived EVs or mPFC tissue." (PMID 40963917, 2025). "Our work has shown that 4T cell-derived EVs-packaged Twist1 induces defective neuronal morphogenesis in the mPFC, providing mechanistic insights into tumor-derived EVs-mediated CID." (PMID 40963917, 2025). "Knockdown of Twist1 in tumor cells significantly alleviated the detrimental effects of tumor-derived EVs on neuronal morphogenesis and prevented their pro-depressant effects." (PMID 40963917, 2025). "Further behavioral tests demonstrated that knockdown of tumor cells-derived Twist1 abolished depressive-like behaviors in tumor-bearing mice." (PMID 40963917, 2025). "Twist1 is a proto-oncogene driving tumor progression and metastasis, and chronic stress induces Twist1 expression in the medial prefrontal cortex (mPFC)." (PMID 40963917, 2025). "TWIST1 seems to be involved in keratinocyte proliferation, tumor promotion, and EMT in a dose-dependent manner." (PMID 40332096, 2025). "We also observed lower expression of PPAR-δ protein in the mPFC of tumor-bearing mice, indicating activation of Twist1/PPAR-δ signaling pathway." (PMID 40963917, 2025). "We conclude that Twsit1 expression in the mPFC induced by tumor-derived EVs is dependent on EVs-mediated Twist1 transfer." (PMID 40963917, 2025). "TWIST1 is known to be opsonized in several human cancers, as well as OC, and assumes an active role in tumor progression and metastasis through diverse chemical processes." (PMID 40424038, 2025). "One of the studies reported that tumor-derived OPN activates Twist1-dependent gene expression by binding to CD44 and αvβ3 integrins on the CAF via Akt and ERK pathway, causing tumor cells to undergo EMT." (PMID 39858015, 2025).